BRCA1 (BRCA1 DNA repair associated)
Diseases named in the same sentence as BRCA1 in open-access papers (continued):
Sharing a sentence is not in itself a finding about the gene and the disease.
breast cancer (continued). "Thus, despite the fact that BRCA1-associated breast tumors tend to be basal-like and triple-negative, both clinical and preclinical studies strongly suggest that luminal progenitor cells are the cell-of-origin of BRCA1-mutated breast cancers." (PMID 30558184, 2018). "BRCA1 is a breast-cancer-susceptibility gene, and a recent study indicated that this gene could be a potential molecular marker in non-small-cell lung cancer." (PMID 29303984, 2018). "Because BRCA1/2 coding mutations only explain 10% of the predisposed families, exhaustive efforts have been undertaken for more than 20 years to identify other loci contributing to breast cancer susceptibility." (PMID 30453575, 2018). "Furthermore, BRCA1-mutated breast cancer is associated with reduced DNMT1 transcription when compared with non-mutated breast cancer." (PMID 30558184, 2018). "It has been hypothesized that BRCA1/2-associated breast cancers have a specific pattern of response according to chemotherapies and their corresponding mechanisms of action." (PMID 30544963, 2018). "Hence, our aims were to characterize a group of Brazilian patients with early onset breast cancer for BRCA1 and BRCA2 germline mutations, as well as for somatic SNVs arising in luminal subtype tumors." (PMID 29854292, 2018). "Importantly, initial studies using colony growth assays suggest that deficiency for BRCA1 in various breast cancer cells causes increased sensitivity to protons." (PMID 31773035, 2018). "BRCA1/2 gene mutations are responsible for approximately two-thirds of hereditary breast cancers." (PMID 29719582, 2018). "So far only two studies have investigated breast cancer risk in Asian women with BRCA1/2 mutations." (PMID 29861850, 2018). "The accumulation of HSP60 into mitochondria, that we observe in our model, is consistent with a pro-survival role of HSP60 and may help to elucidate the pathways that lead to apoptosis suppression in BRCA1 mutated breast cancer cells." (PMID 29584711, 2018). "Similarly, while BRCA1 does significantly increase risk of breast cancer, germline mutations of this gene only account for 3% of all breast cancer cases (Whittemore, Gong & Itnyre, 1997)." (PMID 29761043, 2018). "While most BC are sporadic in nature, approximately 5–10% are attributed to genetics, arising from autosomal dominant mutations in specific cancer genes, the strongest of which are the two breast cancer susceptibility genes BRCA1 and BRCA2 (collectively named “BRCA”)." (PMID 29782524, 2018). "Breast cancers (BC) associated with germline mutations of BRCA1/2 represent 3–5% of cases." (PMID 30544963, 2018). "BRCA1 deficiency may perturb the differentiation hierarchy present in the normal mammary gland and is associated with the genesis of breast cancers that are genomically unstable and typically display a basal-like transcriptome." (PMID 28427147, 2017). "In the case of male breast cancer, PAHs may increase the risk of breast cancer specifically in men carrying a BRCA1 or BRCA2 mutation." (PMID 28865460, 2017). "Additionally, women who are offered testing whose mother or sister had a HER2 positive breast cancer will get little reassurance regarding breast cancer risk from a negative test unless there is also a strong additional family history suggestive of BRCA1/2." (PMID 27796713, 2017). "In addition to breast cancer, males with BRCA1 or BRCA2 pathogenic variants face increased lifetime risks for prostate and pancreatic cancers." (PMID 28008555, 2017). "As for ovarian cancer, first proof-of-concept trials have shown a significant activity of PARP inhibitors in women with advanced breast cancer and BRCA1-2 mutations, reporting ORR to olaparib nearly to 40% and median PFS 5.7 months in the overall population and ORR of 54% in TNBC patients." (PMID 28055979, 2017). "Due to the high expression of β-hCG, we hypothesized that β-hCG might induce tumorigenicity in BRCA1 mutated breast cancer." (PMID 28869585, 2017).
breast cancer (continued). "Current risk estimation models enable the identification of women who are at elevated risk for breast cancer through genetic testing for BRCA1, BRCA2, and other mutations, as well as other potential genetic susceptibilities made evident by family histories of the disease." (PMID 28340626, 2017). "Qualitative research to evaluate how women adapt to and view BRCA1/BRCA2-related breast cancer risk after ovarian cancer could further inform genetic counseling practice." (PMID 28780755, 2017). "Germ-line BRCA1 mutations are associated with significantly increased breast cancer incidence." (PMID 28649985, 2017). "It has also been suggested that basal-like breast cancers in BRCA1 deficient women may potentially arise from K5+ luminal progenitors." (PMID 28147318, 2017). "BRCA1 deficiency is known to play a role in breast cancer development." (PMID 28968398, 2017). "Approximately 5 to 10% of women with breast cancer carry a deleterious mutation in BRCA1 or BRCA2 (BRCA1/2 hereafter) and may be at an increased risk for recurrence of breast cancer in the same or opposite breast." (PMID 28770017, 2017). "Part of the rational for this line of research has been that HR- breast cancers are also more commonly diagnosed among carriers of mutations in the BRCA1 gene, providing some evidence for germline genetic risk factors in the development of specific breast cancer subtypes." (PMID 29333472, 2017). "The IGF2 genetic variants can influence the death risks of breast cancers with BRCA1/2 mutations." (PMID 28415743, 2017). "Given the increase in both local and systemic tumor incidence in mice, we conclude that ID administration of cisplatin under these conditions cannot upfront be regarded as a safe alternative prophylactic therapy to prevent BRCA1-associated breast cancer formation in humans." (PMID 28977823, 2017). "However, data on breast cancer risk in BRCA1/BRCA2 carriers after ovarian cancer are limited as a result of the poor overall survival." (PMID 28780755, 2017). "In addition, presence of breast cancer among mother and daughter was seen in all three groups, with a greater propensity for such phenomenon among patients in the BRCA1-pathogenic group (p = 0.055)." (PMID 27926510, 2017). "CHD4 deficiency was shown to reduce the recruitment of homologous recombination repair factor BRCA1, and it impaired the efficiency of homologous recombination repair, which could affect the treatment of breast cancer characterized by BRCA1/BRCA2 mutations." (PMID 28649742, 2017). "Co-inheritance of MTHFR 677C>T with high-penetrance causative mutations in the BRCA1/2 genes may increase the risk of early-onset breast/ovarian cancer, while mutation 1298 A>C in the same gene is associated with sporadic breast cancer." (PMID 28241424, 2017). "Next, we created HR-deficient MCF7 breast cancer cells by transiently depleting BRCA1." (PMID 29145865, 2017). "In fact, approximately, 70% of breast cancers with BRCA1 germline mutations are the TN subtype." (PMID 29152070, 2017). "5191C > A, T1691K) in BRCA1 have both been found to cause breast cancer." (PMID 28100260, 2017). "Women with an abnormal BRCA1 gene have up to an 80% higher risk of developing breast cancer." (PMID 28972307, 2017). "Mutations in BRCA1 are associated with familial as well as sporadic aggressive subtypes of breast cancer, but less is known about whether BRCA1 expression or subcellular localization contributes to progression in population-based settings." (PMID 28863181, 2017). "An alternative non-invasive way to prevent BRCA1-associated breast cancer may be local prophylactic treatment via the nipple." (PMID 28977823, 2017).
breast cancer (continued). "The difference may be related to different genetic susceptibility among different ethnic groups, as demonstrated for breast cancer susceptibility genes (BRCA1 or BRCA2) mutations previously." (PMID 29216920, 2017). "In order to examine a system undergoing chronic pathophysiological stress, we also investigated T575 phosphorylation in HCC1937 cells, human breast cancer cells bearing two loss of function alleles of BRCA1, a gene encoding a large E3 ubiquitin ligase involved in DNA damage repair." (PMID 28542436, 2017). "It is known that up to 10% of breast cancers may be caused by inherited mutations in breast cancer susceptibility genes, including BRCA1/2 and PALB2." (PMID 29023372, 2017). "In addition to BRCA1/2, genes with an established role in breast cancer, other predisposing genes such as CHEK and PALB2 were evaluated for a possible association with the risk of breast cancer, although their frequency and penetrance was significantly lower." (PMID 29093764, 2017). "Furthermore, germline mutation in BRCA1 gene carriers have a cumulative risk of developing breast cancer ranging from 44% to 68% by 70 years of age." (PMID 27926510, 2017). "Here, the main objective was to evaluate Nestin expression in larger breast cancer series and to explore whether this marker can predict BRCA1 associated cancers." (PMID 28439082, 2017). "By applying multiple logistic regression with stepwise variable selection, using P values as a selection criterion, the HGSC subtype and personal history of breast cancer remained as independent predictive factors for both pathogenic germline variants of BRCA1/2 and any tested genes." (PMID 29348823, 2017). "The BRCA1 gene mutation, caused by a frame shift, could be in close proximity to an MS gene, which would explain why many researchers have found more breast cancer cases in MS patients than expected." (PMID 28932368, 2017). "Disease-associated variants are mainly protein-truncating mutations, whereas a few missense substitutions are reported to perturb its interaction with breast cancer susceptibility proteins BRCA1 and BRCA2, which play essential roles in homology-directed repair (HDR)." (PMID 29387807, 2017). "Breast Cancer susceptibility genes 1&2 (BRCA1&2) are involved in DNA repair and cell cycling." (PMID 29262604, 2017). "In conclusion, BRCA1/2 mutations were associated with bilateral breast cancer and BRCA1 promoter methylation may have a prognostic effect on TNBC." (PMID 29152070, 2017). "In addition, the BRCA1 mutation (c.981_982del) in the study is a founder mutation which has been previously reported in the Southern Chinese breast cancer patients." (PMID 29152070, 2017). "In a small case-only study of 23 men with breast cancer, four of whom were carriers of a BRCA1/2 mutation, BRCA1/2 carrier status interacted with history of ever having driven trucks professionally to enhance the risk of developing breast cancer (COR = 25.5; 95% CI = 1.1–1415)." (PMID 28865460, 2017). "Importantly, attenuation of Pol II pausing can mitigate R-loop accumulation and reduce incidence of mammary tumour development due to BRCA1 deficiency." (PMID 28649985, 2017). "The role of ANRIL in regulation of DNA damage response makes it likely for it to have a critical role in breast cancer pathogenesis given that BRCA1, the most well-known breast cancer susceptibility gene mainly participates in DNA damage-induced cell cycle checkpoint activation and DNA repair." (PMID 28580310, 2017). "In conclusion, we present evidence in the present study that CTSO is a new factor of importance for tamoxifen efficacy as a chemopreventive agent in women at high risk of developing breast cancer as well as evidence for a potential mechanism by which this effect involves BRCA1." (PMID 28968398, 2017). "Mutations of BRCA1 or BRCA 2 genes can increase the risk to develop breast cancer." (PMID 28881705, 2017). "BRCA1 mutation has been associated with the basal like breast cancer subtype." (PMID 28427429, 2017).
breast cancer (continued). "Using genetic mouse-models, we and others identified the RANKL/RANK system as a key regulator of sex hormone, BRCA1-mutation, and oncogene-driven breast cancer and we proposed that RANKL/RANK might be involved in the initiation of breast tumors." (PMID 28002811, 2017). "Several studies have investigated the risk of breast cancer in BRCA1/2 mutation carriers." (PMID 28680148, 2017). "The ER-positive PRS had a stronger association with male breast cancer in BRCA1/2 mutation carriers than did the ER-negative PRS, which was in line with the observation that the majority of male patients with breast cancer among BRCA1/2 mutation carriers are ER positive." (PMID 28448241, 2017). "In BRCA1 mutation-associated breast cancers, c-Kit is required for the growth and survival of the tumor cells, and c-Kit activity may be downregulated to allow normal differentiation in adult tissue." (PMID 28573141, 2017). "It has been hypothesized that promoter methylation may be a main epigenetic mechanism underlying inactivation of the BRCA1 gene in sporadic breast cancer." (PMID 29152070, 2017). "Moreover, we and others have recently reported that RANKL/RANK also control breast cancer development in scenarios of BRCA1 mutations." (PMID 28002811, 2017). "In breast cancer, this mostly involves defective repair of DNA double-stranded breaks by homologous recombination (HR), e.g. as is known to occur in tumor cells arising in carriers of either BRCA1 or BRCA2 germline mutations." (PMID 28679371, 2017). "Consequently, HOTAIR can be an important regulator of gene expression in breast cancer associated with BRCA1 mutations." (PMID 29469819, 2017). "Interestingly, studies have shown that about 30∼40% of patients with sporadic breast cancer have complete loss or significantly reduced expression of BRCA1 protein despite carrying an intact BRCA1 gene." (PMID 29156836, 2017). "Cells that lack BRCA1/2 to repair these lesions, could tend to more error-prone mechanisms, resulting in an increasing risk to breast cancers." (PMID 29152070, 2017). "In addition, most BRCA1 mutation-associated breast cancers possess a molecular signature of basal-like cancers." (PMID 28813639, 2017). "The work described here, along with previously published work, indicates that activity of certain transcriptional regulatory elements and CpG methylation both represent important mechanisms by which the ER gene is typically inactive in breast cancers associated with BRCA1 mutations." (PMID 28270739, 2017). "Moreover, it has been recently shown that women with high genetic breast cancer risk due to BRCA1 mutations appear to be exposed to increased RANKL." (PMID 28002811, 2017). "Other age-related co-variables such as primary sclerosing cholangitis and the potential presence of breast cancer susceptibility genes 1/2 (BRCA1/2) mutations may be enriched in those <40 years and may confound OS outcomes." (PMID 28403829, 2017). "BRCA1/2 mutations were also significantly associated with bilateral breast cancer (p = 0.043)." (PMID 29152070, 2017). "It is known that a synthetic viability conferred by 53BP1 loss may play a role in the development of BRCA1-deficient breast cancer." (PMID 29047390, 2017). "The BRCA1 p.Pro346Ser was associated with breast cancer risk in Chinese women [5 out of 859 Chinese breast cancer patients (0.6%) and 2 out of 1,055 Chinese controls (0.2%), OR = 3.3; 95% CI, 0.6–17.3; p = 0.15], but the results were not statistically significant." (PMID 28222693, 2017). "Based on individual factors, we then discussed how her absolute risk of breast cancer over the five years following diagnosis may be lower than this, due to evidence suggesting a reduction in breast cancer risk after ovarian cancer diagnosis in BRCA1 carriers." (PMID 28780755, 2017).
breast cancer (continued). "In women with BRCA1/2 associated breast cancer, contralateral prophylactic mastectomy (CPM) markedly reduces the risk of breast cancer in the opposite breast and may impact survival." (PMID 28770017, 2017). "The BRCA1 p.Arg762Ser may be associated with breast cancer risk with a marginal significance (p = 0.06)." (PMID 28222693, 2017). "By contrast, in a transgenic murine breast cancer model, nonsynonymous missense mutation in the Brca1 RING domain (C61G) was associated with poorer response to cisplatin and PARP inhibitor therapy than a complete Brca1 knockout, despite similar tumour morphology and copy number alterations." (PMID 29203787, 2017). "For example, the BRCA1 carriers at the 90th percentile of the ER-negative breast cancer PRS had an estimated breast cancer risk of 19% by age 40 years and 39% by age 50 years, compared with 5% by age 40 years and 21% by age 50 years for carriers at the 10th percentile of the PRS." (PMID 28376175, 2017). "Denosumab, a monoclonal antibody to the receptor activator of nuclear factor-κB ligand (RANKL), might be a novel preventative therapy for BRCA1-mutation carriers at high risk of developing breast cancer." (PMID 28388533, 2017). "Interestingly, such mutations were observed not only in patients with BRCA1/2-mutant breast cancers that were resistant to PARP inhibitors, but also patients who had platinum resistant disease." (PMID 28829366, 2017). "BRCA1 mutations are clinically associated with the development of basal-like breast cancers." (PMID 27793013, 2017). "In a phase II study in patients with advanced ovarian or breast cancer associated with a germline BRCA1/2 mutation, continuous dosing of single-agent oral rucaparib led to a higher rate of response than intermittent intravenous (i.v.)dosing (response rate, 18% vs 2%)." (PMID 28222073, 2017). "Our study also suggests that BRCA1 p.Arg762Ser may be associated with increased risk of breast cancer but other methods or larger studies are required to determine a more precise estimate of breast cancer risk." (PMID 28222693, 2017). "Interestingly, few pathogenic variants were identified in ATM and BRCA1, which are commonly mutated in female familial breast cancer." (PMID 28008555, 2017). "Some evidence points out that the epigenetic regulation of the BRCA1 gene may contribute to breast cancer risk." (PMID 28594926, 2017). "This was not confirmed by another report on the ovarian response to IVF stimulation in a combined group of BRCA1/2 mutation carriers undergoing fertility preservation because of breast cancer and asymptomatic BRCA1/2 mutation carriers undergoing IVF with preimplantation genetic diagnosis (PGD)." (PMID 28831696, 2017). "Understanding the relationship between germline and tumour genetics is important in patients where early-onset familial breast cancer or differences in drug response and survival outcome cannot be explained by mutations in the major tumour suppressor genes, BRCA1 and BRCA2." (PMID 28241424, 2017). "The cumulative risk for breast cancer by age 70 has been reported to 45–60% for BRCA1 mutation carriers and 27–55% for BRCA2 mutation carriers with a corresponding risk for ovarian cancer of 31–59% and 6–16.5% for BRCA1 and BRCA2 mutation carriers, respectively." (PMID 28096903, 2017). "Women with a functional BRCA1 mutation have up to an 80% risk of developing breast cancer." (PMID 28863181, 2017).